PIK3CA (phosphatidylinositol-4,5-bisphosphate 3-kinase catalytic subunit alpha)
Diseases named in the same sentence as PIK3CA in open-access papers (continued):
Sharing a sentence is not in itself a finding about the gene and the disease.
metastatic disease (continued). "A third limitation may be that sequencing only two common hotspots on the PIK3CA gene may miss other genetic variations that could occur during the evolution of progressive metastatic disease, and which may have been shared by the CTCs and metastases." (PMID 24947048, 2014). "However, higher HS values of KRAS, HER2, and PIK3CA were observed in metastatic tumors than in unpaired primary tumors, and heterogeneity between primary and metastatic tumors in copy‐number alterations may partly contribute to the differences." (PMID 29518290, 2018). "Interestingly, patients who received palbociclib for metastatic disease were less likely to have detectable ESR1 mutations in cfDNA but this was not the case for PIK3CA mutations (p-value = 0.01)." (PMID 30083595, 2018). "Recent advances include the use of CDK 4/6 inhibitors or PIK3CA inhibitor in the clinic; however, few immunotherapy trials have been conducted in HR+ HER2− metastatic disease." (PMID 36077811, 2022). "The expression of CD8A was increased in primary tumors with neoantigens in RYR3 and DNAH7 and in recurrent/metastatic tumors with neoantigens in TTN and PIK3CA." (PMID 33796222, 2021). "In the recurrent/metastatic tumors, patients with neoantigens in TTN, PIK3CA, and USH2A increased CD3+ CD8+ infiltration approximately 3-fold compared to patients without neoantigens in these genes." (PMID 33796222, 2021). "There were three genes (PIK3CA, USH2A, and TTN) containing neoantigens in the recurrent/metastatic tumors." (PMID 33796222, 2021). "Similarly, our study found that the frequencies of EGFR, KRAS, HER2, BRAF, and PIK3CA mutations in TKI‐naive samples and the frequencies of sensitizing EGFR and T790M mutations in TKI‐relapsed samples showed no statistical differences between unpaired primary and metastatic tumors." (PMID 29518290, 2018).
overgrowth syndrome (69 papers, 2017 to 2026). A group of syndromes caused by genetic birth defects that may lead to the development of malignancies. "PIK3CA-specific inhibitors, such as BYL719, are already under investigation for treating other PIK3CA-mutated tumors and PIK3CA-related overgrowth syndromes (e.g., CLOVES)." (PMID 40361470, 2025). "While most cases of overgrowth syndromes can be explained by gain-of-function mutations in PIK3CA, recent studies have reported PIK3R1 mutations in some patients with overgrowth syndromes and vascular malformations." (PMID 40389643, 2025). "Somatic mosaicism of PIK3R1 and PIK3CA are associated with vascular anomalies and overgrowth syndromes." (PMID 38541623, 2024). "CLOVES syndrome (Congenital Lipomatous Overgrowth, Vascular malformations, and Epidermal nevi ) is an overgrowth syndrome caused by mosaic activating mutation in gene PIK3CA, which is also designated as PROS." (PMID 39080810, 2024). "PIK3CA-related malformations can be divided as overgrowth syndromes caused by PIK3CA mutations which are typically called PROS, and non-syndromic common and combined LMs (ccLMs)." (PMID 37658401, 2023). "Klippel-Trenaunay syndrome (KTS) was demonstrated as a mosaic activating PIK3CA mutations related overgrowth syndrome." (PMID 35154272, 2022). "Several overgrowth syndromes with overlapping clinical manifestations involving a number of mutations in the PIK3CA gene have been identified." (PMID 36142903, 2022). "Alpelisib has indeed been proven effective for the treatment of PROS (PIK3CA-related overgrowth syndromes) since it acts on PIK3CA activating variants." (PMID 35807022, 2022). "The role of Alpelisib has also been identified outside cancer in PIK3CA-related overgrowth syndromes (PROS) which are caused by mosaic gain-of-function mutations in the PIK3CA gene." (PMID 33801659, 2021). "Gain-of-function PIK3CA variants in overgrowth syndromes thus provide a strong rationale for targeted PI3K/AKT/mTOR inhibition as a therapeutic strategy in PROS." (PMID 34385668, 2021). "It is the p110α subunit, encoded by PIK3CA, that is by far the most commonly mutated and activated in cancer and overgrowth syndromes." (PMID 34040190, 2021). "Consistent with our report, the most commonly observed PIK3CA somatic variants in PIK3CA-related overgrowth syndromes (PROS) are p.His1047Arg, p.His1047Leu, p.Glu545Lys and p.Glu542Lys." (PMID 33054853, 2020). "This paradox remains to be explained, but is supported by the identification of PIK3CA mutations, particularly in the kinase domain, in overgrowth syndromes that lack any malignant transformation." (PMID 32195332, 2020). "Somatic activating mutations in PIK3CA have been identified in both isolated LMs and those associated with several overgrowth syndromes." (PMID 33634164, 2020). "With advances in DNA sequencing technology, somatic mosaic variants of PIK3CA have also been identified as causative in several overgrowth syndromes." (PMID 32778138, 2020). "Recently, patients with lipomatous tumors associated with a related spectrum of syndromes caused by mosaic activating PI3K mutations (PIK3CA-related overgrowth syndrome, PROS) were successfully treated with the novel PI3K inhibitor alpelisib (BYL-719)." (PMID 31627436, 2019). "Recently, lipomas associated with PIK3CA-related overgrowth syndrome were successfully treated with the novel PI3K inhibitor alpelisib." (PMID 31627436, 2019). "Somatic PIK3CA variants cause abnormal activation of this pathway, and patients with PIK3CA aberration show overgrowth syndromes (e.g., CLOVES syndrome and MCAP syndrome)." (PMID 31263565, 2019). "The importance of the activating mutations in PIK3CA is further highlighted by the identification of gain-of-function PIK3CA mutations in a range of human tissue overgrowth syndromes." (PMID 31443495, 2019).
overgrowth syndrome (continued). "It is only recently, however, that we have learned of rare, but generally benign overgrowth syndromes caused by postzygotic activating mutations in PIK3CA, the gene encoding p110α." (PMID 30197175, 2018). "The term “PIK3CA – related overgrowth spectrum” (PROS) has gained popularity in recent literature to describe a group of overgrowth syndromes/disorders caused by somatic PIK3CA mutations." (PMID 30180809, 2018). "Somatic activating mutations within the PIK3CA gene have been recently detected in sporadic lymphatic and venous malformations, and in vascular malformations (VM) associated to overgrowth syndromes, such as CLOVES and Klippel–Trenaunay syndrome." (PMID 29352118, 2018). "For example, PIK3CA mutations associated with overgrowth syndromes are often similar to those observed in cancer, but these patients do not seem to be predisposed to cancer." (PMID 28353628, 2017). "The identification of PIK3CA mutations has already led to investigational use of PI3K inhibitors in related overgrowth syndromes, suggesting that similar approaches might benefit macrodactyly patients in the future." (PMID 40993711, 2025). "Additionally, venous and/or capillary malformations frequently occur in overgrowth syndromes associated with PIK3CA pathogenic variants, known collectively as the PIK3CA-related overgrowth spectrum (PROS)." (PMID 39728742, 2024). "However, a next-generation sequencing panel for overgrowth syndromes on peripheral blood identified a known pathogenic variant in the PIK3CA gene (NM_006218.3:c.2176G>A, p.Glu726Lys), present at a 24% variant allele frequency in the tested specimen." (PMID 38813336, 2024). "This overgrowth syndrome is unique and is caused by the somatic PIK3CA mutation c.3140A>G." (PMID 30180809, 2018). "The reasons for hyperplasia of lymphatics have long been unknown, however, recently it has been shown that lymphatic malformations (LM), isolated and in combination with other overgrowth syndromes, are mostly caused by activating mutations in the PIK3CA gene." (PMID 29985963, 2018). "In addition to tumorigenesis, aberrant PIK3CA was also found in benign overgrowth syndromes: it was first identified as a critical gene associated with excessive scarring in a study that was conducted among patients with PIK3CA-related overgrowth syndromes." (PMID 38179473, 2024). "Cellular mosaicism is a particular observation in overgrowth syndromes (e.g., in BWSp and PIK3CA-related overgrowth disorders), as several of them exhibit overgrowth only of parts of the body or even organs." (PMID 38894719, 2024). "The p110α-specific inhibitor BYL719 was also successfully applied for the treatment of patients with PIK3CA-related overgrowth syndrome, which gives hope to patients with LMs." (PMID 33964933, 2021). "PIK3CA-related overgrowth syndromes are mosaic multisystem mTORopathies characterized by congenital lipomatous overgrowth, vascular malformations and skeletal abnormalities." (PMID 34632383, 2021). "Treatment with alpelisib (BYL719), a selective PIK3CA inhibitor improved clinical outcomes in individuals with PIK3CA-related overgrowth syndromes." (PMID 34632383, 2021). "In this context, ERAS adds up to the list of genes whose mutation can lead to overgrowth syndromes (as AKT, PIK3CA, PTEN) or RASopathies (as H-RAS, RASA1, NF1 and RAF1, among others)." (PMID 34771750, 2021). "It has been reported improved HF syndrome with no substantial side effects when using PI3K/AKT inhibitors as a treatment of PIK3CA-related overgrowth syndrome." (PMID 34026868, 2021).
overgrowth syndrome (continued). "A child with HME in the context of PIK3CA-related overgrowth syndrome had reduced seizures and improved cognitive engagement at school following targeted treatment with miransertib (ARQ 092), an orally available AKT inhibitor." (PMID 34632383, 2021). "This inhibitor also demonstrates an anti-proliferative effect in fibroblasts isolated from PIK3CA-related overgrowth syndromes." (PMID 33634164, 2020). "Then, mosaicisms were recognized as other causative mechanisms of overgrowth syndromes, and several of the genes involved, including AKT1, PTEN, and PIK3CA, have been identified." (PMID 32778138, 2020). "A recent report on the treatment of patients with CLOVES (part of the PIK3CA-related overgrowth syndromes) using the PIK3CA inhibitor BYL719, shows promising results." (PMID 33634164, 2020). "Based on these findings, a phase I/II clinical trial is investigating the use of miransertib in PIK3CA-related overgrowth syndromes and other VAs." (PMID 33634164, 2020). "For instance, in some overgrowth syndromes such as PIK3CA-related overgrowth spectrum (PROs), even advanced genetic testing such as next-generation sequencing may be negative when performed from blood samples, and not from the affected tissue." (PMID 38791606, 2024). "Some overgrowth syndromes characterized by lateralized overgrowth have been associated with an increased risk of developing tumor, such as Beckwith–Wiedemann syndrome (BWS), PIK3CA-associated overgrowth syndrome, Proteus syndrome, and PTEN hamartoma tumor syndrome." (PMID 36980758, 2023). "Propranolol could be applied as an adjuvant therapy for reducing vascular symptoms, but a PIK3CA inhibitor would be the primary therapeutic strategy for PIK3CA-related overgrowth syndrome." (PMID 36175890, 2022). "Treatment of patients with CLOVES (a PIK3CA-related overgrowth syndrome) with the PIK3CA inhibitor BYL719P leads to improved symptoms with a decrease in the size of their VAs, and improved cardiovascular measures such as congestive heart failure, cardiac hemihypertrophy, and scoliosis." (PMID 35574555, 2022). "It is increasingly used for complex VAs and PIK3CA-related overgrowth syndromes." (PMID 35574555, 2022). "Because PIK3CA-related overgrowth syndromes often display somatic mosaicism, quantitative pyrosequencing was undertaken in a blood sample matched to the tumour with a somatic PIK3CA variant in order to rule out a low level of constitutional mosaicism." (PMID 33012783, 2021). "Similarly, the Pan-ALK inhibitor ARQ 092 (Miransertib) showed promising results on a cohort of 6 patients with PIK3CA-Related Overgrowth Syndrome." (PMID 34112235, 2021). "It has recently been shown that treatment with low doses of a selective inhibitor of Class I PI3K catalytic subunit p110α, the protein product of the PIK3CA gene, can yield dramatic therapeutic benefits for patients with CLOVES and PROS (a spectrum of PIK3CA-related overgrowth syndromes)." (PMID 33431926, 2021). "Recent study identified that somatic and mosaic gain-of-function mutations of the phosphatidylinositol-4,5-bisphosphate 3-kinase Catalytic Subunit Alpha (PIK3CA) gene were found in FAVA, and FAVA belongs to the spectrum of PIK3CA-related overgrowth syndromes (PROS)." (PMID 32711543, 2020). "A wider classification of ‘PIK3CA-related pathology spectrum’ is presented which includes cancer, benign skin lesions/tumors, Cowden syndrome, isolated vascular malformations and various overgrowth syndromes." (PMID 30180809, 2018). "Furthermore, the paracrine mechanisms elucidated here may be relevant to other PIK3CA-related overgrowth syndromes and could inform strategies for promoting tissue regeneration and wound healing in various contexts." (PMID 40595500, 2025).
overgrowth syndrome (continued). "PIK3CA-related overgrowth syndromes (PROS) are an umbrella term that refers to a very large spectrum of conditions frequently associated with MEG/HMEG caused by a common genetic signature, namely gain of function mutations in PIK3CA gene leading to activation of the PI3K-AKT-mTOR pathway." (PMID 35096710, 2021). "Disorders which feature LM, including overgrowth syndromes such as congenital lipomatous overgrowth with vascular, epidermal and skeletal anomalies (CLOVES) and Klippel-Trénaunay syndrome (KTS), are also frequently associated with somatic mutations in the PIK3CA gene." (PMID 33634164, 2020). "So have most overgrowth syndromes that present with confined overgrowth of one or a few regions of the body (e.g., BWSp Hemihyperplasia, PHTS, PS, PIK3CA, PWS, KTS, PKWS and Proteus syndrome) the molecular defects in only a subset of cells (i.e., a mosaic distribution of the mutation)." (PMID 38894719, 2024). "Recent exome sequencing studies reported somatic activating PIK3CA gene mutations in LPN with or without associated macrodactyly/overgrowth, leading to an establishment of the concept of PIK3CA-related “overgrowth syndromes”." (PMID 37067587, 2023). "Localized overgrowth syndromes such as macrodystrophia lipomatosa have been recognized as a part of overgrowth spectrum disorders related to phosphatidylinositol-4,5-bisphosphate 3-kinase catalytic subunit alpha (PIK3CA) whose genotype-phenotype correlation has not been sufficiently understood." (PMID 30362331, 2019).
thyroid cancer (69 papers, 2006 to 2025). "PIK3CA is more typical of aggressive thyroid cancer types or advanced thyroid cancer, most commonly coexisting with BRAF mutation." (PMID 40226091, 2025). "The mechanisms of resistance to BRAF inhibitors in thyroid cancer include PIK3CA mutations that hyperactivate ERK when BRAF is inhibited." (PMID 40129883, 2025). "Mutations affecting components of the PIK3CA-AKT-mTOR pathway have been observed in 2-11% of poorly differentiated thyroid cancers and in 12-39% of ATC." (PMID 39744583, 2025). "The frequency of PIK3CA mutations and amplifications varies across thyroid cancer subtypes, with higher rates observed in PDTC and ATC." (PMID 40363930, 2025). "The p110 subunit, which is encoded by PIK3CA, has been extensively researched in thyroid cancer and is frequently mutated in various cancers." (PMID 38313845, 2023). "Studies have shown that in advanced iodine-refractory thyroid cancer patients, PIK3CA mutations are more commonly found, especially in those who develop metastasis or experience recurrence." (PMID 38313845, 2023). "It is worth noting that thyroid cancer patients with mutations in PIK3CA or AKT1 almost always also have BRAF mutations, indicating an interaction between the RAS/BRAF/MAPK pathway and the PI3K/AKT pathway in driving thyroid cancer development." (PMID 38313845, 2023). "This provided the rationale for our study to identify the potential role of PIK3CA mutations in the progression from well-differentiated to undifferentiated thyroid cancer." (PMID 35193694, 2022). "The specific role of PIK3CA mutations coexisting with other driver mutations in thyroid cancer has been poorly investigated." (PMID 33799953, 2021). "The genetic alterations reported in the PIK3CA gene in thyroid cancer include gene amplification and, less commonly, mutations." (PMID 32751138, 2020). "Studies conducted to elucidate the role of PIK3CA mutations in the clinicopathological parameters and prognosis point that these mutations have minimal association with the prognosis of thyroid cancers." (PMID 31905960, 2019). "Contradictory findings are reported in the literature regarding the role of PIK3CA gene mutations in thyroid cancers." (PMID 31905960, 2019). "Subsequent studies have shown varying prevalence of mutation in different subtypes of thyroid cancer, but PIK3CA mutations were the most commonly found in anaplastic cancers and the least observed in papillary." (PMID 31905960, 2019). "On the other hand, thyroid cancer patients with PIK3CA mutations were shown to have a distinct pathological profile as PIK3CA mutations are likely to arise during the tumor progression." (PMID 31289610, 2019). "Given the occurrence of PIK3CA mutations in all stages of thyroid carcinoma, it supports the implication of the PI3K/AKT signaling pathway in both the initiation and progressive dedifferentiation of the disease." (PMID 28117295, 2017). "In thyroid cancer, PIK3CA mutations are rare in PTCs (0–5% depending on series) but more frequent in poorly differentiated and anaplastic thyroid cancer (from 11 to 23%)." (PMID 25214840, 2014). "Mutation in PIK3CA is also seen in the pathogenesis of thyroid cancer relatively common in anaplastic thyroid carcinoma." (PMID 23768168, 2013). "PIK3CA mutations were most frequent in endometrial, ovarian, colorectal, breast, cervical, squamous cell cancer of the head and neck, chondroma, thyroid carcinoma and in cancer family syndrome." (PMID 23768168, 2013). "PIK3CA copy number gain occurs more frequently than genetic mutations of PIK3CA or PTEN in thyroid cancer." (PMID 23077520, 2012).